SCD (stearoyl-CoA desaturase)
Diseases named in the same sentence as SCD in open-access papers (continued):
Sharing a sentence is not in itself a finding about the gene and the disease.
Obesity (continued). "An intriguing model proposes that obesity is attenuated by lowering the amount of hepatic and/or adipose stearoyl-CoA desaturase-1 (SCD1), the rate-limiting enzyme in biosynthesis of monounsaturated fatty acids, which are preferred for triglyceride assembly." (PMID 21345233, 2011). "SCD-1 activity index in adipose tissue is best reflected by 16:1/16:0-ratio in serum FFA, but associations with obesity and insulin resistance differ between these pools." (PMID 19712485, 2009). "Paton and Ntambi demonstrated SCD-l to be a key enzyme in regulating hepatic lipogenesis and lipid oxidation; therapeutic manipulation of SCD-1 can be of benefit in treatment of obesity and metabolic syndrome." (PMID 19761624, 2009). "Moreover, CYP1B1 deficiency attenuated HFD‐induced obesity and improved glucose tolerance due to the reduced expression of different adipogenic genes such as PPARγ, CD36, FAS, and SCD‐1 and increased expression of genes involved in lipolysis." (PMID 39806854, 2025). "It is noteworthy that the high level of SCD-1 expression and subsequently higher levels of monounsaturated fatty acids have also been related to higher cancer death in patients affected by obesity, conferring more benefits to the use of nisin as a health-protective agent." (PMID 36765351, 2023). "Numerous studies have demonstrated the inevitable importance of stearoyl-CoA desaturase-1 (SCD1) in the metabolic and signaling pathways, making its role unquestionable in several prevalent human diseases, including obesity, diabetes, fatty liver, and cardiovascular diseases." (PMID 36292669, 2022). "In addition, the activation of AHR/CD36 pathway promotes hepatic steatosis in mice, while inhibiting the activity of AHR and altering the expression levels of CYP1B1, PPARα, and SCD-1 that attenuate the diet-induced obesity and hepatic steatosis in mice." (PMID 34722615, 2021). "In a study sample of participants with overweight and obesity, it would be reasonable to expect lower diet quality and elevated plasma SCD activity indices and SAAs at baseline, and we would thus expect a clearer effect of the test meals used in the present pilot study." (PMID 32778150, 2020). "SCD is a key enzyme in the conversion of polyunsaturated fatty acids (PUFAs) to monounsaturated fatty acids (MUFAs), and it has been shown to be overexpressed in adipose tissue in obesity." (PMID 32967728, 2020). "Disruption of SCD gene profoundly reduces the development of obesity by impairing lipid synthesis." (PMID 31861338, 2019). "The obesity-related gene stearoyl-CoA desaturase-1 (Scd1) is one such gene." (PMID 29757144, 2018). "In various animal models of obesity, SCD activity is abnormally elevated in the adipose tissue." (PMID 28570716, 2017). "Furthermore, elevated expression levels of the human SCD1 gene are found to correlate both with the SCD enzyme activity, and obesity." (PMID 27562731, 2016). "Hitherto, no study has addressed the effect of sleep deprivation on cytosine DNA methylation of SCD1 that might have implications for SCD activity, endogenous lipid biosynthesis and development of obesity." (PMID 27562731, 2016). "The enzyme stearoyl-CoA desaturase (SCD), which is predominantly expressed in the liver, plays a central role in the desaturation of saturated fatty acids (FAs), thus having important implications in the metabolism of FAs and development of obesity." (PMID 27562731, 2016). "Stearoyl-CoA desaturase (SCD) may play an important role in the pathogenesis of obesity-induced insulin resistance in humans and mice." (PMID 25938677, 2015). "Whether a lower SCD-16 index protects against diet-induced obesity is an interesting possibility that warrants further investigation." (PMID 23298201, 2013). "Since high SCD-1 activity is associated with decreased fat oxidation and increased FA synthesis, and since an SCD-1 knockout leads to resistance to DIO, SCD-1 has been proposed as a potential target in the treatment of obesity." (PMID 23298201, 2013).
Obesity (continued). "Accumulating evidence suggest that Stearoyl-CoA-Desaturase (SCD-1) enzyme activity may be regulated differently in adipose tissue and liver, and its link with insulin resistance and obesity may differ between these pools." (PMID 19712485, 2009). "Indeed, SCD1 converts saturated into monounsaturated fatty acids, and enhanced SCD-1 activity and the resulting higher amounts of monounsaturated fatty acids have been associated with obesity and insulin resistance." (PMID 39841244, 2025). "Thus, the HFD-induced decrease in SCD activity may serve as a mechanism for protection against diet-induced obesity by inhibiting de novo lipogenesis and increasing fat oxidation, as observed in SCD1 knockout mice." (PMID 39201497, 2024). "Consequently, SCD knockout mice are protected from fat diet-induced obesity." (PMID 34991486, 2022). "In addition to obesity, SCD action may also involve the development of Alzheimer-type neurodegeneration at molecular levels, as evident by the increased expression of SCD mRNA in subjects with AD." (PMID 28621759, 2017). "This miRNA alleviates obesity-initiated MASLD by repressing the expression of fatty acid synthase and stearoyl-CoA desaturase." (PMID 39424772, 2025). "An increase in blood SCD activity positively correlates with plasma TAG, obesity, and insulin resistance." (PMID 36982607, 2023). "Thus, SCD may be a key regulator of energy metabolism with a role in obesity and dyslipidemia." (PMID 35631379, 2022). "In mesenteric adipose tissue, lipogenic genes such as SREBP-1c, ACC, FAS, and SCD-1 are upregulated by an HFD compared with a ND, and inhibition of this upregulation exerts anti-obesity effects." (PMID 33158191, 2020). "On day 4, the network showed inhibition of the upstream regulator N-CoR in BPS-treated cells which leads to activation of adipogenic genes such as SCD, PLIN1, ACACB, CIDEC, ADIPOQ and FABP, leading to obesity." (PMID 27685785, 2016). "Because SCD-1 appears to be strongly involved in the etiology of metabolic syndrome, understanding the regulation of this enzyme may assist in the development of new therapies and prevention strategies for several chronic diseases, such as obesity, diabetes, dyslipidemia and arteriosclerosis." (PMID 26046927, 2015). "The expression of many lipogenic genes, such as acetyl-CoA carboxylase (ACC) and stearoyl-CoA desaturase (SCD), is transcriptionally regulated by sterol regulatory element-binding protein-1 (SREBP-1) and then activates expression of the target gene in obesity." (PMID 25202333, 2014). "In this experiment we demonstrate that obesity-prone rats have a significantly higher SCD-16 index, significantly higher proportions of the SCD-1 product 16:1n-7, but a lower proportion of LA in adipose tissue." (PMID 23298201, 2013). "SCD-1 and CD36 are involved in fatty acid uptake and oxidation, and mice that lack SCD-1 are lean and resistant to obesity." (PMID 23533476, 2013). "Our results help to further elucidate the role that SCD-1 plays in driving susceptibility to diet-induced obesity, as it has not yet been determined whether differences in SCD-1 between OP and OR rats exist in the adipose tissue and whether these changes occur simultaneously across lipid fractions." (PMID 23298201, 2013). "SCD-1, a key rate-limiting enzyme in FFA desaturation, is significantly elevated in the liver of obese mice on high-fat diets, and it is a potential therapeutic target for obesity, diabetes, and other metabolic diseases, including NAFLD." (PMID 34122607, 2021).
Obesity (continued). "SCD is a key enzyme in the conversion of polyunsaturated fatty acids (PUFAS) to monounsaturated fatty acids (MUFAS), and it has been shown to be overexpressed in adipose tissue in obesity and metabolic disorders." (PMID 30642114, 2019). "Moreover, we found that obesity induced lipogenesis genes in db/db mice, as demonstrated by the increased transcription of genes such as PPARγ, SREBP-1c, ACOCA, FASN, and SCD." (PMID 31246177, 2019). "As the current study cohorts were BMI-matched and not hypertriglyceridemic, it is apparent that systemic SCD activity was elevated in the type 2 diabetic cohort beyond that expected by obesity alone." (PMID 23144998, 2012). "Thus, it is presumed that SCD inhibition rather than FAS inhibition contributed more to the anti-obesity effects of PPF." (PMID 31514294, 2019). "In brief, obesity increases MUFA content and decreases PUFA content (specifically n-3 and n-6 PUFA) at both compartments, but also increases the ratios of MUFA/SFA and C18:1/C18:0 in visceral fat (i.e., increases desaturation index and Stearoyl-CoA desaturase 1 activity; SCD1)." (PMID 29534532, 2018). "Preclinical and epidemiological data indicate that activation of stearoyl-coA-desaturase (SCD-1), a Δ9 fatty desaturase responsible for the conversion of SFA to Monounsaturated fatty acids (MUFA) is potentially a critical factor both in the development of obesity and cancer including breast cancer." (PMID 29271901, 2017). "In addition, the food intake, insulin sensitivity and fat mass in mice with the adipose SCD-1 deletion were similar to that of the controls, and they were not protected from diet-induced obesity." (PMID 26046927, 2015). "However, a limitation of the study was not having carried out an assessment of the expression of obesity-related genes such as family peroxisome proliferator-activated receptor (PPAR), adipocyte fatty acid binding protein (AFABP, also known as aP2 and FABP4), and stearoyl-CoA desaturase (SCD)." (PMID 39408365, 2024).
Hepatic steatosis (214 papers, 2009 to 2026). Steatosis is a term used to denote lipid accumulation within hepatocytes. "SCD-1 deficiency protects against high-fat-, high-carbohydrate-, and leptin deficiency-induced obesity and hepatic steatosis." (PMID 34017254, 2021). "The development of other diseases, such as cancer, bone fractures and hepatic steatosis, has also been associated with SCD-1 expression." (PMID 26046927, 2015). "Interestingly, low hepatic SCD activity is associated with fatty liver and insulin resistance in obese humans." (PMID 31694213, 2019). "In this animal model, downregulation of SCD-1 was associated with hepatic steatosis." (PMID 26046927, 2015). "Furthermore, SCD deficiency mimicked the ability of 6-G to reduce lipid accumulation in HF-induced HepG2 cells, and impaired the improvement in hepatic steatosis brought about by 6-G treatment in HFD supplemented with oleic acid diet-induced SCD1 knockout mice." (PMID 39457074, 2024). "SREBP-1c might increase FAS and SCD-1 mRNA levels to cause hepatic steatosis." (PMID 29932129, 2018). "Therefore, although Scd1-null mice are resistant to hepatic steatosis, they are more susceptible to liver injury while increased SCD-1 expression during NAFLD reflects a compensatory beneficial effect on increasing MUFA synthesis and storage of excessive FFAs as triglycerides." (PMID 20300478, 2009). "The synthesis of mono-unsaturated fatty acid from saturated fatty acetyl Co-A is catalyzed by SCD-1, and its deletion prevents the development of fatty liver." (PMID 39458470, 2024). "Aramchol is an oral modulator of liver stearoyl-coenzyme A desaturase-1 (SCD-1), which is involved in fatty acid biosynthesis, liver steatosis, and fibrosis." (PMID 38891828, 2024). "Consistent with previous reports, our study showed that an increase in inflammatory cytokines is a preceding inducer in the development of hepatic steatosis, and long‐term GT and Ex or combination inhibit the expression of SCD‐1 in the liver of HF mice." (PMID 38370081, 2024). "Taken together, our present study demonstrated that 6-G inhibits DNL by targeting SCD to alleviate fructose diet-induced hepatic steatosis." (PMID 39457074, 2024). "DHA suppressed acute ethanol-induced hepatic steatosis and downregulated the levels of stearoyl-CoA desaturase 1 (SCD) and inflammatory cytokines, such as TNF-α and IL-6, but did not affect reactive oxygen species production." (PMID 38791514, 2024). "In conclusion, our research suggests that 6-G mitigates hepatic DNL by targeting SCD to ameliorate fructose-induced hepatic steatosis." (PMID 39457074, 2024). "SCD-1, a common isoform of this enzyme, is a crucial gene in hepatic steatosis and plays a straightforward role in intracellular fat accumulation in NAFLD." (PMID 35498726, 2022). "Such connection relies on OLMALINC’s ability to promote the expression of its adjacent TG-gene recognized as stearoyl-CoA desaturase (SCD), which is known to be up-regulated in hepatic steatosis and NAFLD." (PMID 36232885, 2022). "C–X–C motif chemokine ligand 3, cholesterol 7α-hydroxylase, and stearoyl-CoA desaturase, which are involved in the development of fatty liver, were significantly upregulated." (PMID 35498726, 2022). "Third, H-UDCA/RSV/EZE treatment was more effective in reducing hepatocyte ballooning and mRNA expression of SCD-1 compared with L-UDCA/RSV/EZE treatment in HFD-induced hepatic steatosis." (PMID 35982712, 2022). "Our results found T090 can cause liver steatosis at a concentration of 2 mg/kg/d and increase the key lipogenic factors including SREBP-1c, FAS, and SCD-1." (PMID 35959429, 2022). "The decrease in hepatic steatosis was accompanied by decreased expression of lipogenic genes, including Srebp1c and stearoyl-CoA desaturase 1 (Scd1), and increased expression of β-oxidation-related genes, such as Pparα and Cpt-1α." (PMID 33794740, 2021).
Hepatic steatosis (continued). "It has been demonstrated that SCD activity is positively correlated with export of lipids from the liver and negatively correlated with hepatic steatosis." (PMID 33921866, 2021). "Several studies have established a role for SCD-1 in promoting hepatic steatosis, insulin resistance, and obesity." (PMID 31980623, 2020). "Research studies have demonstrated that the knockdown of SCD prevents liver steatosis in wild-type mice." (PMID 31340583, 2019). "In contrast, short-term inhibition of tissue specific hepatic SCD increased hepatic TG content and enhanced insulin signaling, but the long-term inhibition decreased hepatic steatosis." (PMID 21869929, 2012). "Mice with a disruption in SCD-1 (stearoyl-CoA desaturase 1) have reduced adiposity, resistance to diet-induced weight gain, reduced hepatic steatosis, and increased insulin sensitivity." (PMID 21698093, 2011). "SCD-1 regulates partitioning of saturated fatty acids (SFAs) between MUFAs present in simple hepatic steatosis and SFAs present during hepatic steatohepatitis and fibrotic livers." (PMID 20300478, 2009). "In contrast, network members promoting development of hepatic steatosis, such as PPARγ, SCD, SREBF1, ACOX1, CIDEC and CFD (adipsin) are repressed during early phase and induced during the late phase of hepatic response to HF diets." (PMID 19680557, 2009). "Interestingly, however, mice fed a methionine- and choline-free diet develop hepatic steatosis but also exhibit robust suppression of hepatic SCD-1 expression." (PMID 38755480, 2024). "Overall, 6-G inhibits DNL by targeting SCD to alleviate diet-induced hepatic steatosis." (PMID 39457074, 2024). "This evidence suggests that 6-G alleviates HF-induced hepatic steatosis by targeting SCD." (PMID 39457074, 2024). "Besides, SCD-1 is known to play a critical role in lipid-mediated signaling and the formation of hepatic steatosis." (PMID 32143613, 2020). "Additionally, the desaturation index C16:1/C16:0 and C18:1/C18:0, which is used to estimate the SCD-1 activity was significantly increased which further supports the involvement of SCD-1 in hepatic steatosis." (PMID 30026586, 2018). "The reduction in hepatic steatosis was accompanied by decreased expression of the lipogenic genes sterol regulatory element binding transcription factor 1c (Srebf1c) and stearoyl-CoA desaturase 1 (Scd1)." (PMID 29599925, 2018). "Also, high-fat diet-induced hepatic steatosis in obese mice were associated with inhibited PPARα activity and increased expressions of SREBP-1c, as well as its target genes, FAS and SCD-1." (PMID 30398974, 2018). "However, on a high-carbohydrate diet, SCD-1 −/− mice showed less weight gain and a reduction in plasma triglycerides compared with the controls, and they were also protected from diet-induced liver steatosis." (PMID 26046927, 2015). "Indeed, based on the results obtained, the ablation of both SCD1 and SCD2 would be necessary in the liver tissue to ascertain the requirement of SCD proteins in hepatic steatosis and hepatocarcinogenesis." (PMID 24069385, 2013). "Diabetes-associated NEFA patterns indicate increases in SCD activity and decreases in VLCPUFA chain shortening, which may indicate impaired hepatic insulin sensitivity and/or fatty liver disease." (PMID 23144998, 2012). "SCD-1 knockout mice are resistant to hepatic steatosis and hepatic insulin resistance." (PMID 20300478, 2009). "Furthermore, endogenous MUFA production via stearoyl-CoA desaturase-1 (SCD1) has been shown to protect against hepatic steatosis and insulin resistance, reinforcing the view that MUFA enrichment plays a compensatory and protective role in age-related metabolic regulation." (PMID 40323517, 2025). "Furthermore, hepatic C16:0 content was related with hepatic steatosis or inflammation and hepatic SCD-1 could convert C16:0 to C18:1 to reduce the toxicity of C16:0." (PMID 29932129, 2018).